KLF4 (KLF transcription factor 4)
Diseases named in the same sentence as KLF4 in open-access papers (continued):
Sharing a sentence is not in itself a finding about the gene and the disease.
lymphedema (2 papers, 2021 to 2025). Excess fluid collection in tissues, causing swelling. "Nevertheless, preadipocytes derived from lymphedema subjects exhibited differential expression of GDF15, the marker of mitochondrial stress, and of KLF4, KLF6, INHBA and ZNF423, i.e. genes implicated in adipogenesis, when compared with cells from healthy women." (PMID 33854130, 2021).
non-alcoholic steatohepatitis (2 papers, 2018 to 2025). "In nonalcoholic steatohepatitis conditions, RORA induces Kruppel-like factor 4 (KLF4) to promote anti-inflammatory macrophage polarization, thereby ameliorating disease progression." (PMID 40874179, 2025).
oropharynx carcinoma (2 papers, 2021 to 2022). A primary or metastatic malignant neoplasm that affects the oropharynx. "In HPV-negative oropharynx carcinoma KLF4 was low represented in most of all tumor cell nuclei, together with a diffuse localized membranous E-cadherin reaction." (PMID 35219646, 2022).
ovarian tumor (2 papers, 2016 to 2024). "We determined that pluripotency factors KLF4 and MYC were upregulated in carboplatin-resistant ovarian tumor tissue compared to sensitive tumor tissues." (PMID 38796478, 2024).
pneumococcal pneumonia (2 papers, 2021 to 2024). A febrile disease caused by STREPTOCOCCUS PNEUMONIAE. "Here, we investigated the impact of KLF4 expression in myeloid cells such as macrophages and PMNs on inflammatory response and disease severity in a pneumococcal pneumonia mouse model and in patients admitted to hospital with CAP." (PMID 34589087, 2021). "Here, we investigated the impact of KLF4 expression in myeloid cells such as phagocytes on disease severity and regulation of the inflammatory response in a pneumococcal pneumonia mouse model." (PMID 34589087, 2021). "Thus, KLF4 expression in myeloid cells impacts survival rate and clinical severity of pneumococcal pneumonia in mice." (PMID 34589087, 2021). "To conclude, the expression of KLF4 in monocytes/macrophages and PMNs might reduce the release of IL-10 in patients with pneumococcal pneumonia and, thereby, strengthen the early innate immune response against S. pneumoniae." (PMID 34589087, 2021). "Thus, KLF4 expression in myeloid cells increases bacterial clearance, reduces bacteremia, promotes alveolar-capillary barrier integrity and reduces lung tissue damage in murine pneumococcal pneumonia." (PMID 34589087, 2021). "Thus, KLF4 in myeloid cells such as macrophages and PMNs is an important regulator of the early pro-inflammatory immune response and, therefore, a potentially interesting target for therapeutic interventions in pneumococcal pneumonia." (PMID 34589087, 2021). "In summary, the obtained results identify the transcription factor KLF4 in myeloid cells such as macrophages and PMNs as important regulator of the early pro-inflammatory innate immune response and, thereby, early disease severity in murine and human pneumococcal pneumonia." (PMID 34589087, 2021). "In the present study, we identified the transcription factor KLF4 in myeloid cells such as phagocytes as potent mediator of the early pro-inflammatory innate immune response and, therefore, as potentially interesting target for therapeutic interventions in pneumococcal pneumonia." (PMID 34589087, 2021). "Thus, in line with our in vitro findings, in vivo expression of KLF4 in myeloid cells increases the release of the pro-inflammatory cytokines TNF-α, KC and IL-1β and decreases the release of the anti-inflammatory cytokine IL-10 in murine pneumococcal pneumonia." (PMID 34589087, 2021).
pneumonia (2 papers, 2021 to 2025). An acute, acute and chronic, or chronic inflammation focally or diffusely affecting the lung parenchyma, caused by an infection in one or both of the lungs (by bacteria, viruses, fungi, or mycoplasma.). "Patients with higher KLF4 gene expression had a lower SOFA score as indicator for less severe pneumonia (mainly due to better oxygenation, higher mean arterial pressure, unaltered level of consciousness) and lower anti-inflammatory IL-10 serum levels upon hospital admission." (PMID 34589087, 2021).
T-cell leukemia (2 papers, 2013 to 2015). A malignant disease of the T-lymphocytes in the bone marrow, thymus, and/or blood. "KLFs 4, 5 and 10 are important in T-cell activation and trafficking and KLF4 may function as a tumor suppressor in adult T-cell leukemia, KLF2 promotes memory B-cell differentiation and KLF3-deficient mice display a myeloproliferative disorder." (PMID 24130502, 2013). "Therefore, reactivation of KLF4 in T-ALL cells may pave a new road for T cell leukemia therapy." (PMID 25644173, 2015).
Abdominal obesity (1 paper, 2016). Excessive fat around the stomach and abdomen. "In the process of inflammation induced by abdominal obesity, whether KLF4 and KLF15 play an important role and whether the A2bAR correlates with KLF4 and KLF15 are not found." (PMID 27199507, 2016).
acneiform dermatitis (1 paper, 2022). Cutaneous eruptions resembling acne, characterized by the presence of papulonodules, pustules, comedones, or cysts in the face, trunk, and extremities. "This is rather intriguing as MEK inhibitors including trametinib is associated with acneiform dermatitis, owing to off-target effects on KLF4/NF-κB-dependent transcription of inflammatory cytokines." (PMID 35847840, 2022).
acute leukemia (1 paper, 2025). A clonal (malignant) hematopoietic disorder with an acute onset, affecting the bone marrow and the peripheral blood. "BAALC binder of MAP3K1 and KLF4 (BAALC), a regulator of developing neuroectoderm tissues overexpressed in acute leukemia and GBM, and a target of SOX2 in differentiated GBM cells, was upregulated in HF2303 SDCs." (PMID 39919036, 2025).
acute pancreatitis (1 paper, 2025). An acute inflammatory process that leads to necrosis of the pancreatic parenchyma. "While we also used the caerulein model of acute pancreatitis to corroborate our findings, our study can attribute the observed changes in DNA methylation and gene expression to cell-intrinsic expression of KLF4." (PMID 40156071, 2025).
adenovirus infection (1 paper, 2020). "We tried to knockout KLF4 in rat smooth muscle cells using adenovirus infection." (PMID 32807822, 2020). "To determine whether Tanshinone II A regulates smooth muscle cell phenotypic switching through mediated KLF4 expression, we first overexpressed of KLF4 in rat aortic smooth muscle cells by adenovirus infection and the expression efficiency validated by real time PCR." (PMID 32807822, 2020).
adult T-cell leukemia (1 paper, 2014). "KLF4 is also known to be inactivated by methylation in adult T-cell leukemia." (PMID 25037230, 2014).
Alcoholic cirrhosis (1 paper, 2021). "Alcoholic cirrhosis possibly may increase expression of KLF4." (PMID 34884173, 2021).
alcoholic liver diseases (1 paper, 2023). A disorder caused by damage to the liver parenchyma due to alcohol consumption. "Previous studies have also suggested that KLF4, also a member of the KLF family, can regulate the polarization of M1/M2 macrophages in alcoholic liver disease." (PMID 37600783, 2023).
amyloid (1 paper, 2025). "The previous implication of KLF4 and EGR1 in human AD and the conservation of this Klf4-Egr1 regulatory module across different time points and between tau- and amyloid-based AD models points to its fundamental importance in the pathological process." (PMID 40336141, 2025).
ankylosing spondylitis (1 paper, 2024). An autoimmune chronic inflammatory disorder characterized by inflammation in the vertebral joints of the spine and sacroiliac joints.
Arthritis (1 paper, 2018). Inflammation of a joint. "KLF4 deficiency attenuated arthritis severity in both CIA and CAIA mice." (PMID 29997611, 2018). "In summary, we showed here that KLF4 regulates development of experimental arthritis in CIA and CAIA models." (PMID 29997611, 2018). "Mean arthritis score of KLF4Rg−/− mice was much lower than that of KLF4+/+ mice at day 8 to day 16 after collagen antibody injection." (PMID 29997611, 2018). "By contrast, overexpression of KLF4 in CIA mice aggravated arthritis when compared with wild-type CIA mice." (PMID 29997611, 2018). "We next examined the severity of arthritis in vivo by altering KLF4 expression." (PMID 29997611, 2018). "The severity of arthritis in KLF4 knockout mice was less than that in wild-type mice." (PMID 29997611, 2018). "After confirming transcription of KLF4 in SPL and paw cells in vivo, we scored the severity of arthritis in the PBS-, mcMock-, and mcKLF4-injected groups." (PMID 29997611, 2018).
Autoimmunity (1 paper, 2017). The occurrence of an immune reaction against the organism's own cells or tissues. "Thus, Mule-mediated ubiquitination of the novel substrate KLF4 regulates T-cell proliferation, autoimmunity and antiviral immune responses in vivo." (PMID 28084302, 2017).
B-cell acute lymphoblastic leukemia (1 paper, 2020). A neoplasm of lymphoblasts committed to the B-cell lineage, typically composed of small to medium-sized blast cells. "With this technique at hand, we analyzed the role of the transcription factor Krüppel-like factor 4 (KLF4) in B-cell acute lymphoblastic leukemia (B-ALL) PDX models at different disease stages." (PMID 32944247, 2020).
B-cell neoplasm (1 paper, 2024). A group of heterogeneous lymphoid tumors generally expressing one or more B-cell antigens or representing malignant transformations of B-lymphocytes. "Indeed, YY1 binds to the Kruppel-like factor 4 (KLF4) promoter, inducing proliferation and differentiation of B-cell neoplasm in B-NHL." (PMID 38339244, 2024).
bacteremia (1 paper, 2021). "Likely as a result of the altered early immune response, we found that lung tissue damage, rates of bacteremia, clinical symptoms of infection and necessity for euthanasia due to reached level of pain was significantly higher in myeloid KLF4 knockout mice compared to the corresponding wildtypes." (PMID 34589087, 2021).
benign meningioma (1 paper, 2016). A grade I, slowly growing meningioma. "On the basis of recent whole genome-sequencing approaches, novel candidates in benign meningiomas have been identified which include: TRAF7 (the receptor-associated factor 7), KLF4 (Kruppel-like factor 4), AKT1 (v-akt murine thymoma viral oncogene homolog 1) and SMO (Smoothened)." (PMID 27429002, 2016).
benign vascular tumor (1 paper, 2015). "The IHC scores for all proteins tested except Klf4 were significantly increased in the malignant and borderline vascular tumors relative to the non-diseased controls, and were surprisingly very similar to the levels observed in benign vascular tumors." (PMID 26412983, 2015).
bipolar disorder (1 paper, 2020). A disorder of the brain that causes unusual shifts in mood, energy, activity levels and the ability to carry out day-to-day tasks. "For example, lithium treatment, used in patients affected by bipolar disorder and likely exerting neuroprotective effects, changes the expression levels of several genes in astrocytes, including Krüppel-like factor 4 (KLF4) and PARK2 co-regulated (PARKRG)." (PMID 32646031, 2020).
brucellosis (1 paper, 2024). Brucellosis is a bacterial infection that spreads from animals to people via unpasteurized dairy products or by exposure to contaminated animal products or infected animals. "The expression levels of multiple genes (e.g., PIM1, PIM3, KLF4) involved in the ‘negative regulation of cell apoptotic process’ were higher in brucellosis patients than in controls." (PMID 39135683, 2024).
Cachexia (1 paper, 2022). Severe weight loss, wasting of muscle, loss of appetite, and general debility related to a chronic disease. "We also observed a clear decrease in genes dominantly regulating fat cell differentiation, including CEBPB, CEBPD, BMP2, and KLF4, in vPreA in cachexia group, as compared to patients without cachexia." (PMID 36376273, 2022).
cataract (1 paper, 2012). Partial or complete opacity of the crystalline lens of one or both eyes that decreases visual acuity and eventually results in blindness. "We first efficiently reprogrammed HLECs from age-related cataract patients to iPSCs with OCT-4, SOX-2, and KLF-4." (PMID 22403680, 2012).
cerebral aneurysm (1 paper, 2023). "TNFα can also induce cerebral SMC phenotypic changes through KLF4 and Myocardin, which may contribute to cerebral aneurysm formation." (PMID 37686377, 2023).
cerebral edema (1 paper, 2018). "Similar to miR-330-5p that down-regulates Tim-3, miR-200b expression was induced in cerebral edema, concomitant with M1 polarization and reduction in KLF4 level." (PMID 30060570, 2018).
cervical neoplasms (1 paper, 2014). "KLF4 transactivates the expression of the cell cycle inhibitor p27Kip, which is associated with malignant transformation and aggressive phenotypes of cervical neoplasms." (PMID 24551169, 2014).
chronic superficial gastritis (1 paper, 2020). "The H-scores of HNF4α, CDX2, and KLF4 protein were 33.0 ± 7.6 vs. 122.1 ± 8.3 (P < 0.01), 17.0 ± 5.6 vs. 60.4 ± 5.9 (P < 0.01), and 58.8 ± 7.3 vs. 129.7 ± 6.5 (P < 0.01) in gastritis vs. IM tissues, respectively." (PMID 32655894, 2020). "To further confirm the relationship between TGR5 and metaplasia markers in IM, we detected TGR5, HNF4α, CDX2, and KLF4 expression using three consecutive slides of gastric tissue including 120 cases IM and 67 cases of chronic superficial gastritis by IHC." (PMID 32655894, 2020).
clear cell renal cell carcinoma (1 paper, 2013). "Krüppel-like factor 4 (KLF4) is a transcription factor with diverse functions in various cancer types; however, the function of KLF4 in clear cell renal cell carcinoma (ccRCC) carcinogenesis remains unknown." (PMID 23861801, 2013).
dental caries (1 paper, 2025). The decay of a tooth, in which it becomes softened, discolored, and/or porous. "Some pSS patients exhibit extensive tooth loss and multiple dental caries, suggesting that KLF4 might be involved in the mechanisms of dental damage in pSS patients." (PMID 41181153, 2025).
EBV infection (1 paper, 2015). "Here we show that a cellular transcription factor known to promote epithelial cell differentiation, KLF4, induces differentiation-dependent lytic EBV infection by binding to and activating the two EBV immediate-early gene (BZLF1 and BRLF1) promoters." (PMID 26431332, 2015). "We propose that the increased expression of KLF4 and BLIMP1 that occurs during normal epithelial cell differentiation promotes lytic EBV infection." (PMID 26431332, 2015). "Collectively, these results suggest that the expression of KLF4 and BLIMP1 correlates with lytic EBV infection in the tongue." (PMID 26431332, 2015).
ependymoma (1 paper, 2022). A WHO grade II, slow growing tumor of children and young adults, usually located intraventricularly. "On the other hand, we selected the KLF4 gene because it is widely expressed in neural stem cells, some of which are shown in the ependymomas, and plays a significant role in their self-renewal, also involved in reprogramming of somatic cells to pluripotency." (PMID 34854470, 2022). "We analyzed herein the methylation levels of KLF4 and 17.1% of our ependymoma tissues were hypermethylated." (PMID 34854470, 2022). "We think that the methylation status of KLF4 may play a role in the oncogenesis of ependymomas but further studies with wider series are needed to address whether KLF4 hypermethylation can be an epigenetic signature." (PMID 34854470, 2022). "Material and Method: DNA methylation status of CDKN2A, RASSF1A, KLF4 and ZIC2 genes were quantitatively analyzed with pyrosequencing in 44 ependymoma tumor tissues." (PMID 34854470, 2022). "In the present study, we analyzed the gene-specific methylation profiles of the CDKN2A, RASSF1A, KLF4 and ZIC2 genes in the ependymoma tumor tissues." (PMID 34854470, 2022).
glomerulosclerosis (1 paper, 2022). A hardening of the kidney glomerulus caused by scarring of the blood vessels. "We found that transient induction of transcription factor Kruppel-like factor 4 (KLF4) in podocytes causes a sustained decrease in albuminuria in a murine model of glomerulosclerosis." (PMID 35024974, 2022). "Recently, we demonstrated that the DNA DSB repair factor KAT5, which acts coordinately with KLF4, is indispensable for maintaining healthy podocytes and that loss of KAT5 in podocytes causes massive proteinuria and glomerulosclerosis with increased DNA damage sites and DNA methylation in podocytes." (PMID 35024974, 2022).
Gorlin syndrome (1 paper, 2020). "When the reprogramming factors OCT4/3, SOX2, KLF4 and c-MYC were introduced into 4.0 x 105 cells, iPSCs generated from four patients with Gorlin syndrome were successfully generated and designated as G11-, G12-, G36- and G72-iPSC." (PMID 32436863, 2020).
helminth infection (1 paper, 2020). "Conditional KLF4 deletion within conventional CD8α+-type DCs provided evidence that KLF4 is required to promote Th2 cell responses induced upon HDM challenge or helminth infection, whereas KLF4 deletion did not affect Th1 or Th17 responses in other infection models." (PMID 32714326, 2020).
hemangioblastoma (1 paper, 2020). "One patient from this group (F14) without either TRAF7, KLF4, or AKT1 mutations harbored a germline VHL mutation with VHL copy number loss in the tumor, and developed posterior fossa chordoid meningioma followed by hemangioblastoma 12 years later." (PMID 31963394, 2020).
immune thrombocytopenia (1 paper, 2025). "Similarly, low-dose decitabine enhances M2 macrophage polarization in patients with primary immune thrombocytopenia by increasing KLF4 expression." (PMID 40640934, 2025).
intestinal cancer (1 paper, 2022). "KLF4 is a member of the Krüppel-like factor (KLF) family of proteins and acts as a tumor suppressor in colon, bladder, lung, gastric, and intestinal cancers." (PMID 35774082, 2022).
intraductal papillary mucinous neoplasms (1 paper, 2022). "In a recent study, more KLF4 hotspot driver mutations were identified at high prevalence in low-grade intraductal papillary mucinous neoplasms (IPMNs)." (PMID 35996584, 2022).
invasive carcinoma (1 paper, 2014). A carcinoma that is not confined to the epithelium, and has spread to the surrounding stroma. "The average IHC score of KLF4 staining was 9.30±2.85 in normal cervix and 2.45±2.94 in invasive carcinoma (P<0.05 by 2-tailed t test)." (PMID 24551169, 2014).
ischemic disease (1 paper, 2017). Lack of blood supply to an area of the body, resulting in impairment of tissue oxygenation. "Despite the fact that Klf4 has been implicated in apoptosis, data on Klf4 in ischemic disease are scarce." (PMID 28977827, 2017). "To further elucidate the role of Klf4 in ischemic disease we evaluated downstream targets of Klf4 by qPCR." (PMID 28977827, 2017).